PALB2 (partner and localizer of BRCA2)
Diseases named in the same sentence as PALB2 in open-access papers (continued):
Sharing a sentence is not in itself a finding about the gene and the disease.
ovarian carcinoma (continued). "In 175 probands from a clinic based series of breast and/or ovarian cancer families with no detectable BRCA1/BRCA2 mutations, we have identified two mutations in PALB2: one, c.3113G > A, is known to be deleterious and the other, c.3507_3508delTC (p.H1170Ffs*19), is likely to be deleterious." (PMID 25225577, 2014). "To date, PALB2 gene alterations have not been extensively studied in ovarian cancer patients." (PMID 20122277, 2010). "However, this study utilized a panel consisting of BRCA1/2, PALB2, CHEK2, and ATM only, whereas the GRACE panel was more extensive and included genes not traditionally associated with ovarian cancer, which explains our higher prevalence of P/LP variants overall." (PMID 39061202, 2024). "On the other hand, genetic mutation of PALB2 (another BRCA-Fanconi anemia ovarian cancer-associated gene), whose transcribed protein binds at BRCA1 and RBCA2 at the sites of DNA damage, has been associated with heredity of breast cancer syndrome, but not with ovarian cancer." (PMID 31366178, 2019). "A family history of ovarian cancer was only seen in BRCA1/2 families but not in PALB2 families, where 28.3% of BRCA1 carriers and 12.3% of BRCA2 carriers had a family history of ovarian cancer (p-value = 0.001 and 0.018, respectively)." (PMID 34439348, 2021). "This is the largest study looking at the prevalence of PALB2 PGVs and the CHEK2_1100delC PGV from a single genetics center in patients attending with a personal diagnosis of breast and/or nonmucinous ovarian cancer." (PMID 34113003, 2021). "New findings that RAD52 is essential for cell viability in BRCA1-, PALB2- and BRCA2- and RAD51 paralog-deficient cells, but not in normal cells, suggested that RAD52 may represent an attractive therapeutic target for killing hereditary breast cancer and ovarian cancer cells." (PMID 27649245, 2016).
pancreatic cancer (188 papers, 2010 to 2026). "EI_1109 and her sister, diagnosed with GC, along with a sister who had pancreatic cancer and a brother with colon cancer, all carry the PALB2 p.(Arg414Ter) variant." (PMID 40446793, 2025). "This is exemplified by our first case, in which a patient later developed pancreatic cancer, a malignancy associated with PALB2 germline mutations." (PMID 40948682, 2025). "Although data on pancreatic cancer risk are more limited, current evidence indicates a lifetime risk of approximately 2%–3% in PALB2 carriers, which is significantly higher than that of the general population." (PMID 41049353, 2025). "In recent years, multiple reports have shown that BRCA1, BRCA2 and PALB2 genes, which are known as “the core homologous recombination (HR) genes”, present germline mutations in up to 5% of patients with pancreatic cancer." (PMID 40124650, 2025). "Significant contributors to cancer susceptibility are increasingly recognised in PALB2 mutation carriers, the mutations of which are found in breast and pancreatic cancers." (PMID 41049353, 2025). "Treatment priority shifted to his pancreatic cancer, and he was started on modified fluorouracil/leucovorin/irinotecan (150 mg/m2)/oxaliplatin every 14 days given his PALB2 mutation history." (PMID 40948682, 2025). "There is also a need for additional translational studies to better characterize myeloid and T-cell subsets and activity in BRCA- and PALB2-mutated versus wild-type pancreatic cancer." (PMID 40426860, 2025). "Mutations in PALB2 increase the risk of pancreatic cancer, particularly in individuals with a family history of the disease." (PMID 39409171, 2024). "Rucaparib maintenance is a safe and effective therapy for platinum-sensitive advanced pancreatic cancer with BRCA1/2 or PALB2 pathogenic variant." (PMID 37588193, 2024). "PARP inhibitors are a crucial treatment strategy for patients with BRCA- or PALB2-mutated pancreatic cancer, offering a valuable maintenance therapy option." (PMID 39595558, 2024). "Pathogenic variants in the PALB2 gene significantly increase the risk of developing breast, ovarian, and pancreatic cancers." (PMID 39409938, 2024). "Rucaparib is another PARPi that has demonstrated efficacy in metastatic BRCAm or PALB2 mutated pancreatic cancer." (PMID 39796639, 2024). "There is some evidence of the co-expression of EARS2 with PALB2 in breast and pancreatic cancer and the association of their overexpression with poorer outcomes." (PMID 38052461, 2024). "For example, a patient with advanced pancreatic cancer that responded to talazoparib in the first-in-human phase I study was found to harbor a PALB2 mutation." (PMID 39085400, 2024). "The PALB2-associated hereditary cancer syndrome is also associated with pancreatic cancer, while the BARD1-associated hereditary cancer syndrome is associated with colon cancer." (PMID 37239385, 2023). "The synergistic effect of the PARP inhibitor and of platinum-based chemotherapy was assessed in a randomized phase 2 study including treatment-naive patients with pancreatic cancer with germline BRCA1/2 or PALB2 mutations." (PMID 37366887, 2023).
pancreatic cancer (continued). "PALB2 has also been associated with ovarian and pancreatic cancer; however, our study is the first report of PALB2 PGVs in lung cancer, and further statistical genetic evidence and functional studies are needed to support this association." (PMID 37610374, 2023). "Recently, we reported a low prevalence of PALB2 pathogenic variants (2/150; 1.3%) in a cohort of unselected pancreatic cancer patients from Pakistan." (PMID 37951914, 2023). "A cohort of 29 advanced pancreatic cancer patients with deleterious germline mutations in BRCA1/BRCA2 or PALB2 had longer OS (median OS 21.8 months versus 8.1 months) than matched controls without mutations." (PMID 36975505, 2023). "Previous studies have reported a 1% BC risk and a 3% pancreatic cancer risk for men carrying PALB2 variants by age 80, underlying its relevant role in MBC predisposition and the importance of developing a surveillance protocol for male carriers." (PMID 37347260, 2023). "Germline PALB2 pathogenic variants have been associated with an increased risk of breast, ovarian, and pancreatic cancer." (PMID 38201484, 2023). "One particular variant, c.172_175delTTGT (p.Gln60Argfs), was recurrent in PALB2 carriers and was reported in other studies to be associated with hereditary breast and pancreatic cancer." (PMID 37239058, 2023). "This phase 2 trial evaluates the efficacy of veliparib (ABT-888, PARPi) in 16 patients with previously treated BRCA1/2- or PALB2-mutated pancreatic cancer." (PMID 35328658, 2022). "Cisplatin is a crucial agent for treatment of pancreatic cancer patients with BRCA1/2 or PALB2 mutation." (PMID 35662734, 2022). "BRCA1/2 and PALB2 pathogenetic carriers in heterozygosis have also higher relative risk for pancreatic cancer." (PMID 35454911, 2022). "The results show no confirmed response, suggesting that development of other therapeutics are needed for the pancreatic cancer patients with BRCA1/2 or PALB2 mutations." (PMID 35328658, 2022). "Clinical trials recognize germline PALB2 variants as a sensitive target for PARP-inhibitors in platinum-sensitive advanced pancreatic cancer." (PMID 35685436, 2022). "Recently, PALB2 has also been reported to be associated with increased risks of OC and pancreatic cancer." (PMID 35806485, 2022). "In a study of whole genome sequencing data of pancreatic cancer patients with pathogenic variants of BRCA1/2 or PALB2, signature 3 mutations, and genomic instability were correlated with platinum response." (PMID 35163129, 2022). "Olaparib, a PARPi, is being evaluated in adjuvant setting in a randomized phase II trial for resectable pancreatic cancer with germline BRCA1/2 or PALB2 mutation after perioperative chemotherapy (NCT04858334)." (PMID 35948602, 2022). "Another example is the different pathogenic variants in the gene PALB2 associated with varying levels of risk for breast, ovarian and pancreatic cancers." (PMID 35875659, 2022). "For example, pathogenic BRCA1, BRCA2 and PALB2 variants are associated with both male BC and pancreatic cancer." (PMID 36115878, 2022). "Olaparib, a PARP inhibitor, has been approved by the FDA in pancreatic cancer patients with BRAC1/2 or PALB2 mutations." (PMID 33350171, 2021). "The latest American College of Medical Genetics and Genomics guidelines recommend that pancreatic cancer surveillance should be considered for germline PALB2 pathogenic variant." (PMID 34476650, 2021). "The association between PALB2 germline alterations and risk of developing pancreatic cancer has been also described by other groups." (PMID 33718150, 2021). "Screening for PanIN or IPMN is especially important in people with familial pancreatic cancer, Peutz-Jeghers syndrome, familial atypical multiple mole melanoma syndrome, and genetic mutations like PALB2 or BRCA29." (PMID 33742084, 2021). "In recent years it has become clear that truncating PALB2 variants have been shown to be associated with a high risk for breast, ovarian and pancreatic cancers 50-52." (PMID 34646395, 2021).
pancreatic cancer (continued). "As we highlighted in prior sections, patient selection using platinum-sensitivity plus BRCA or PALB2 mutation status identifies a subset of patients with pancreatic cancer who benefit from PARPi maintenance." (PMID 34572943, 2021). "The PALB2 gene has been associated with Fanconi anemia, pancreatic cancer and hereditary breast cancer." (PMID 33384710, 2020). "Mutations in BRCA1/2 and in Partner and Localizer of BRCA2 (PALB2) genes are reported in approximately 5% to 9% of pancreatic cancer patients." (PMID 32366019, 2020). "Meanwhile, truncating PALB2 variants have also been shown to be associated with an increased risk of familial ovarian and pancreatic cancer." (PMID 33195396, 2020). "Heterozygous loss of PALB2 has also been demonstrated to confer a susceptibility to breast and pancreatic cancer, as PALB2 interacts directly with both BRCA1 and BRCA2 during HR." (PMID 33194896, 2020). "In recent years it has become clear that pathogenic variants in PALB2 are associated with a high risk for breast, ovarian and pancreatic cancer." (PMID 33195396, 2020). "While germline biallelic mutations in PALB2 give rise to Fanconi anemia subtype FA-N, monoallelic mutations predispose to breast and familial pancreatic cancer." (PMID 31586400, 2019). "Since then, more mutations in PALB2 gene have been identified in pancreatic cancer, implying the urgent need of Palb2 pancreatic cancer mouse models to understand its role in pancreatic cancer development." (PMID 31877165, 2019). "While biallelic mutations in the PALB2 tumor suppressor cause Fanconi anemia subtype FA-N, monoallelic mutations predispose to breast and familial pancreatic cancer." (PMID 31586400, 2019). "Among pancreatic tumors of patients with PALB2, as for BRCA1/2 mutation carriers, LOH has been reported." (PMID 31877165, 2019). "Since its identification as a BRCA2 interacting partner, PALB2 has emerged as a pivotal tumor suppressor protein associated to hereditary cancer susceptibility to breast and pancreatic cancers." (PMID 28858227, 2017). "Several reports in the literature indicate the association of PALB2 germline truncating variants with pancreatic cancer (PC)." (PMID 28858227, 2017). "The PALB2 gene (OMIM #610355) is one of the relatively few known high risk pancreatic cancer susceptibility genes associated with familial pancreatic cancer to date." (PMID 26111702, 2015). "PALB2 mutations have also been identified in a small proportion of hereditary pancreatic cancer families." (PMID 26484312, 2015). "An association between germline PALB2 mutation and increased pancreatic cancer risk has also been established." (PMID 24949998, 2014). "Multiple studies have reported melanoma in families harbouring inactivating PALB2 mutations, including individuals with diagnoses of both melanoma and breast or pancreatic cancer." (PMID 24949998, 2014). "This would include patients with FPC or carriers of a mutation in an established high-penetrance PDAC susceptibility gene (e.g., BRCA2 or PALB2) with at least one case of pancreatic cancer in a first-degree relative." (PMID 24624093, 2014). "Recently, PALB2 was reported to be a new pancreatic cancer susceptibility gene as truncating mutations were identified in American patients with familial pancreatic cancer." (PMID 23586058, 2013). "PALB2 mutation carriers of familial pancreatic cancer have to be considered as high-risk individuals with at least 10- to 32-fold increased risk depending on the number of affected family members." (PMID 23586058, 2013).
pancreatic cancer (continued). "ATM and PALB2 variants were recently associated with familial pancreatic cancer (FPC) using exome sequencing (ES)." (PMID 23561644, 2013). "We analyzed a large series of hereditary breast/pancreatic cancer families analysed for PALB2 mutations." (PMID 23935836, 2013). "This pancreatic association was based on the identification of a PALB2 mutation by exomic sequencing and the subsequent PALB2 analysis in additional familial pancreatic cancer patients that revealed a prevalence of 3.1%." (PMID 23935836, 2013). "Considering these studies with our data, the global prevalence of PALB2 mutation in breast/pancreatic cancer families is 1.5% (7 mutations in 467 families)." (PMID 23935836, 2013). "Pancreatic cancer was mentioned at least twice in the family histories of our PALB2 mutation carriers." (PMID 20122277, 2010). "The surveillance recommendations for individuals with PALB2 gene mutations focus primarily on early detection and prevention of breast and pancreatic cancers and are similar to those for BRCA1/2 mutation carriers, given the significantly increased risk associated with these mutations." (PMID 41049353, 2025). "In addition, mutations in the PALB2 gene confer an increased risk of different types of cancers, particularly pancreatic cancer." (PMID 41049353, 2025). "Upstream regulatory mutations in BRCA1 and PALB2 may further influence miR-184’s apoptotic effects in breast and pancreatic cancers, illustrating how its function depends on the dominance of specific pathways or ceRNA dynamics within a given tumour context." (PMID 41379397, 2025). "Furthermore, in cases of TNBC with BRCA1 mutation and pancreatic cancer with BRCA2/PALB2 germline alterations, a more abundant macrophage population, encompassing M1 and M2 subtypes, is evident." (PMID 40830526, 2025). "Lastly, with pre-clinical evidence that immune signaling through the cGAS/STING pathway promotes HRD, it is possible that STING agonists could synergize with PARPis in both BRCA- and PALB2-mutated as well as wild-type pancreatic tumors." (PMID 40426860, 2025). "While mutations in PALB2 genes are known to be oncogenic, the impact on the hazard ratio for pancreatic cancer remains unknown." (PMID 38730578, 2024). "Very few patients with somatic BRCA/PALB2-mutated pancreatic cancer were enrolled in this study." (PMID 39456541, 2024). "The American Society of Gastrointestinal Endoscopy (ASGE) has similar recommendations for patients with BRCA1, BRCA1, and PALB2 mutations to begin screening for pancreatic cancer at the age of 50 years or 10 years younger than the youngest relative with pancreatic cancer." (PMID 39200847, 2024). "Also, the risk for pancreatic cancer in PALB2 heterozygote P/LP carriers is estimated to be 2–3% to age 80 years." (PMID 37686625, 2023). "PALB2 germline mutation increases the risk of breast and pancreatic tumors." (PMID 37313463, 2023). "Somatic mutations of BRCA1, BRCA2 and PALB2 are ~14% in pancreatic cancer." (PMID 35328658, 2022). "While PALB2 bi-allelic variants have been associated to Fanconi’s anemia, monoallelic loss-of-function variants have been reported to be responsible for an increased risk of both breast and pancreatic cancers." (PMID 36035419, 2022). "However, we analyzed just 42 BRCA-negative subjects; moreover, we included many pancreatic cancer patients based on PALB2 association with this kind of cancer." (PMID 35456488, 2022). "Thus, individuals with a pathogenic BRCA2 or PALB2 variant also have a significantly increased risk for pancreatic cancer." (PMID 36292468, 2022). "Genomic instability score calculated based on LOH, large-scale state transitions, and telomeric allelic imbalances was associated with sensitivity to platinum agents in a study of whole genome sequencing data of pancreatic cancer patients with pathogenic variants of BRCA1/2 or PALB2." (PMID 35163129, 2022).